LINC00881 (long independently transcribed non-coding RNA 881)
Synonyms: LIPTER
Gene: Long non-coding RNA gene on chromosome 3 (157,089,634 to 157,381,265, forward strand). Ensembl gene ENSG00000241135.
Diseases named in the same sentence as LINC00881 in open-access papers:
LINC00881 is named in the same sentence as 13 diseases in open-access papers, as found by Europe PMC text mining. Sharing a sentence is not in itself a finding about the gene and the disease. The quoted sentences say what the papers report.
cancer (2 papers, 2023 to 2025). A tumor composed of atypical neoplastic, often pleomorphic cells that invade other tissues. "Our study shows that linc00881 promotes the migration of OS cells to the lung and induces the conversion of normal lung fibroblasts into cancer-associated fibroblasts (CAFs)." (PMID 37990331, 2023).
LINC00881 also shares sentences with these, for which no sentence is quoted: cardiomyopathy (2 papers); metabolic syndrome (2); cardiac hypertrophy (1); diabetes (1); dilated cardiomyopathy (1); heart diseases (1); heart failure (1); hyperglycaemia (1); metabolic disorders (1); Obesity (1); osteosarcoma (1); Tumor (1).